BDNF (brain derived neurotrophic factor)
Diseases named in the same sentence as BDNF in open-access papers (continued):
Sharing a sentence is not in itself a finding about the gene and the disease.
depression (continued). "In addition to their shared genetic background, depression and migraine share genes from the serotoninergic, dopaminergic, and GABAergic systems, as well as variants of the MTHFR (methylenetetrahydrofolate reductase) and BDNF (brain-derived neurotrophic factor) genes." (PMID 38255689, 2024). "On the other hand, some molecular studies demonstrated that effects of these AMP kinases were modulated by CREB/BDNF and Akt/GSK3 signaling pathways, which played important roles in depression." (PMID 38038373, 2024). "Data on BDNF and SAD interaction are scarce, however, it has been reported that serum BDNF concentrations show strong seasonal variation and correlations with the amount of ambient sunlight in persons with a DSM-IV depression diagnosis." (PMID 38473717, 2024). "We suggest that future studies should focus on examining the effects of SNPS on combined depression in coronary artery disease, especially targeting the 5-HTTLPR and BDNF genes of rs6265." (PMID 38745947, 2024). "Brain-derived neurotrophic factor (BDNF), another member of neurotrophic factors, was described as being involved in synaptic plasticity, depression, and increasing survival of dopaminergic neurons of the developing substantia nigra." (PMID 38362105, 2024). "Given the effective increase in the expression of BDNF, ERK1/2 and CREB in the treatment group in the alcoholic cognitive impairment mouse model, HME is expected to improve cognitive function and depression through neuronal recovery and regeneration." (PMID 39126094, 2024). "Moreover, inflammation affects growth factors, such as BDNF in the DG of the hippocampus, resulting in the damage of neuronal integrity, including neurogenesis, long-duration potentiation, and dendritic germination, which is important in the onset of depression." (PMID 38318145, 2024). "Considering this information, our study observes that the physiopathology of depression‐like behavior after ovariectomy includes an increase in NLRP3 and IL‐1β levels and a decrease in BDNF levels in the hippocampal area." (PMID 39443283, 2024). "Based on these facts, the BDNF/TrkB/CREB signaling pathway is acknowledged to play a key role in the development and treatment of depression." (PMID 38337722, 2024). "Present findings highlight PLT-BDNF as more reliable at detecting depression than PTSD in BD, encouraging further study into BDNF variability contextually with immune-inflammatory parameters in wider cohorts of differentially symptomatic bipolar patients." (PMID 38542503, 2024). "Our findings in this pilot study are in line with neuro-evidenced research on the interrelationship between depression, AHN, physical exercise, and BDNF." (PMID 39767394, 2024). "In conclusion, this study identified significant differences in serum BDNF, GDNF, 5-HT, and IL-1β among the HC, PWE, and PWECD groups, suggesting their involvement in epilepsy and comorbid depression." (PMID 39474368, 2024). "The enhanced expression of BDNF, p-ERK1/2 and p-CREB in the hippocampus of mice suffering from alcohol-induced cognitive decline and depression demonstrated the efficacy and potential of high-dose HME treatment as a preventive and therapeutic medicine for ARD." (PMID 39126094, 2024). "Various treatments for depression, such as selective serotonin reuptake inhibitors (SSRIs) and electroconvulsive therapy (ECT), have been shown to increase BDNF levels." (PMID 39568824, 2024). "We recommend that future research focus on studying SNPs’ impact on comorbid depression in coronary heart disease, specifically targeting the 5-HTTLPR and BDNF gene at rs6265." (PMID 38745947, 2024). "The integrated approach, assessing both BDNF and CRP, aims to offer a comprehensive view of the intricate interaction among oxidative stress, inflammatory conditions, and depression in these patients." (PMID 38255209, 2024).
depression (continued). "The brain-derived neurotrophic factor (BDNF), measured using blood samples, has been studied concerning depression and hippocampal volume." (PMID 39767394, 2024). "We evaluated initial serum BDNF, anxiety through the State–Trait Anxiety Inventory (STAI), and the severity of depressive symptoms by the Hamilton Depression Rating Scale (HDRS)." (PMID 39408702, 2024). "The alteration of the level of BAs decreases the expression of farnesoid X receptor to reduce the biosynthesis of brain-derived neurotrophic factor (BDNF), which is one of the significant incentives of depression patients." (PMID 39012662, 2024). "One of the promoters driving the expression of BDNF; promoter IV (BP4), was found to play a role in anxiety and depression-like behaviour when deleted from mice." (PMID 38228888, 2024). "In this respect, clinical and animal studies have highlighted the link between low levels of brain-derived neurotrophic factor (BDNF) and the development of behavioral symptoms of depression." (PMID 38542177, 2024). "Another study showed that neuroinflammation can decrease 5hmC enrichment in the brain-derived neurotrophic factor (BDNF) gene, which is an essential epigenetic element related to depression-like behaviors." (PMID 38410811, 2024). "Brain-derived neurotrophic factor (BDNF) is a factor that implicate in the pathophysiology and treatment of depression and anxiety." (PMID 38907644, 2024). "In this sense, we found a significant interaction between NRN1-rs10484320 and BDNF-rs6265 impacting PANSS general psychopathology, which encompasses symptoms like anxiety, guilt, tension, depression, and disorientation." (PMID 38720004, 2024). "By elevating expression levels of neurotrophins, including BDNF and neurotrophin-3, sesamin alleviated depressive symptoms in a mouse model of CUMS-induced depression." (PMID 39459643, 2024). "Physical activity helps increase the production of the neurotransmitters dopamine, serotonin, and brain-derived neurotrophic factor BDNF, contributing to the treatment of depression." (PMID 38667519, 2024). "Changes in brain levels of GABA, dopamine (DA), acetylcholine (Ach), and brain-derived neurotrophic factor (BDNF), which are markers of anxiety, depression, and behavioral dysfunctions, were observed after DSS induction of the IBD-like condition." (PMID 39456459, 2024). "These alterations in DNA methylation, along with disrupted epigenetic control of genes, such as BDNF and SLC6A4, suggest a possible link between early life experiences, epigenetic changes, and increased vulnerability to depression." (PMID 39194576, 2024). "Previous research has indicated that TMS can modulate levels of BDNF and neurotransmitters (GABA, glutamate, DA, 5-TH) in patients with depressive disorders." (PMID 39176225, 2024). "The study aimed to investigate the effects of multi-strain probiotic supplementation on serum levels of IL-6, BDNF, nerve growth factor (NGF), and aspects of mental health, including depression, fatigue, and pain." (PMID 38137679, 2023). "In other study, oral treatment with sesamin (30 and 50 ppm) increases the amount of 5‐hydroxytryptamine (5‐HT), norepinephrine (NE), neurotrophin‐3 (NT3), brain‐derived neurotrophic factor (BDNF), and improved depression." (PMID 37457142, 2023). "The local infusion of BDNF in the VTA, instead, elicits a depression-like decrease in social interaction." (PMID 37298449, 2023). "In addition, it has been proposed that ALA could act on mood symptoms by upregulating neurotrophic factors, such as the brain-derived neurotrophic factor (BDNF), in animal models of depression, and this action on mood could, in turn, have an impact on cognitive performance." (PMID 36767724, 2023). "In the present study, loganin reversed the CUMS‐induced decrease in the mRNA and protein expression levels of BDNF, PI3K, and Akt in the hippocampus of CUMS‐induced depression‐like mice, which was blocked by TrkB antagonist K252a." (PMID 37408379, 2023).
depression (continued). "In the present study, we aimed at systematically reviewing the literature on the serum and plasma levels of BDNF in DM and its subgroups such as T2DM, DM patients with depression, and patients with retinopathy." (PMID 36787304, 2023). "However, the association between BDNF and depression has not yielded conclusive results." (PMID 37089920, 2023). "Since brain-derived neurotrophic factor plays a mediatory role in the dorsolateral prefrontal cortex plasticity and hippocampal forms such as the long-term potentiation, a reduction in its expression, as witnessed in chronic stress, could be attributed to depression-induced cognitive deficits." (PMID 37426101, 2023). "In short, our study provides novel insights regarding the relationship between BDNF-TrkB signaling, inflammatory factors, and clinical characteristics in MDD, especially the possible role of mBDNF in the neurobiology of the connection between depression and suicidal ideation." (PMID 37626579, 2023). "Although lower BDNF levels during follow-up after ACS were observed in patients with depression, no cause–effect relationship was established between lower serum BDNF levels on the diagnosis of ACS and the subsequent development of depression." (PMID 37895349, 2023). "Our strategy to augment BDNF in CRCI has also been trialed in a number of neurological complications such as AD, Parkinson’s disease, and depression." (PMID 36720792, 2023). "Thus, BDNF and its downstream pathway could probably be suggested as a drug target for depression." (PMID 37252132, 2023). "This study focused on treatment-resistant depression (TRD) treated with ECT, assessing changes in adipokines and BDNF before and after treatment." (PMID 37891727, 2023). "The current investigation aims to investigate the influencing factors of anxiety and depression in MHD patients and their correlation with the expression of BDNF, NT-3, and 5-HT." (PMID 37750080, 2023). "Together, these findings suggest that the basal BDNF/trkB signaling is weaker in the HC and PFC of rats prone to developing a stress-induced depression-like phenotype compared to depression-resilient rats." (PMID 37298449, 2023). "ERK expression would be involved in the intermediate process of BDNF expression, and the inhibition of ERK in the prefrontal cortex and hippocampus leads to depression-like behavior." (PMID 37109699, 2023). "CRTC2 maintains the equilibrium between BDNF and GC and regulates the HPA axis in the context of depression." (PMID 37932977, 2023). "Vitamin D also appears to improve depression-like behavior in animal models, including the CUMS and OVX models, through actions on BDNF and neurotrophic protein (NT)-3/NT-4 signaling pathways and serum corticosterone/adrenal corticotropin (ACTH) levels." (PMID 37836833, 2023). "When conducting subgroup analysis, serum BDNF levels were lower among patients with T2DM (SMD = -1.26, P<0.001), DM and depression (SMD = -1.69, P<0.001), and patients with diabetic retinopathy (DR) vs. controls (SMD = -1.03, P = 0.01)." (PMID 36787304, 2023). "Moreover, a reduction in BDNF was reported in the hippocampus of postmortem brain tissues of MDD and suicide victims while injection of BDNF in the hippocampus reduces depression‐like behavior in rodents." (PMID 36599082, 2023). "To explore the effects of hyperactive autophagy in DG neurons on neuronal BDNF, AHN, and depression-like behaviors, we knocked down Atg5 expression in the hippocampal DG neurons of CORT mice using AAV-hSyn-miR30-shRNA (Atg5)." (PMID 36793868, 2023). "TrkB was a specific binding site for brain derived neurotrophic factor (BDNF) and BDNF was considered a potential neurobiological marker for depression." (PMID 37408379, 2023). "In the present study, we aimed at systematically reviewing the literature on the serum and plasma levels of BDNF in DM and its subgroups such as T2DM, DM patients with depression, and patients with diabetic retinopathy (DR)." (PMID 36787304, 2023).
depression (continued). "Numerous studies have shown that the expression of BDNF and NTF-3 are key targets related to the pathophysiology of depression and anxiety disorders." (PMID 36982280, 2023). "Xanthoceraside, a triterpenoid saponin extracted from Xanthoceras sorbifolia Bunge, activates the BDNF signaling pathway and AHN, thus alleviating CUMS-induced depression." (PMID 38152691, 2023). "Our study results showed that there was a significant correlation between the BDNF level and CDSS score in the patient group, which indicates that BDNF may be associated with the pathomechanism of schizophrenia and the occurrence of depression in schizophrenic patients." (PMID 37013544, 2023). "The results obtained confirm the involvement of the HPA axis, the system of neurotrophic factors (GDNF, BDNF), and inflammation (TNF-α) in the pathogenesis of epilepsy and depression." (PMID 38069144, 2023). "Daily exercise significantly increased brain-derived neurotrophic factor (BDNF) and serum serotonin concentration, which reduce depression symptoms with a p < 0.05." (PMID 37422660, 2023). "In addition to the monoaminergic pathway and BDNF, other mechanisms that may be involved in depression have been reported, such as the GABAergic system alteration, increased expression of postsynaptic serotonin receptors (5-HT1A), decreased calcium influx and increased expression of astrocytes." (PMID 37298210, 2023). "In conclusion, SIRT1 negatively regulates the expression of BDNF, CREB, SYN, and PSD95 through the SIRT1/miR-134 signaling pathway, promoting nerve regeneration and alleviating depression-like behavior." (PMID 37239191, 2023). "We addressed these limitations and knowledge gap by designing a frontal lobe-based CCT, applying it to older adults with moderate to severe depression in an RCT, and examining changes in not only mood and cognition but also BDNF." (PMID 38298930, 2023). "Serum BDNF levels were lower in patients with DM, T2DM, DM with depression, and DM and DR than the controls." (PMID 36787304, 2023). "For depression and other emotion problems, herbal formulas have also been developed in TCM, and these formulas target the BDNF-TrkB, MAPK pathway, etc.." (PMID 36864895, 2023). "Several pieces of evidence show that signaling via brain-derived neurotrophic factor (BDNF) and its receptor, tropomycin receptor kinase B (TrkB), as well as inflammation, play a crucial part in the pathophysiology of depression." (PMID 37626579, 2023). "Generally, BDNF levels of brain regions are lower in major depression disorder (MDD) patients, and antidepressant treatment may increase the BDNF level back to normal." (PMID 37396946, 2023). "We assessed mood using the Hamilton Rating Scale for Depression (HAM-D) and Patient Health Questionaire-9 (PHQ-9), cognition using the Montreal Cognitive Assessment (MoCA), and serum BDNF levels at baseline and follow-up." (PMID 38298930, 2023). "In mouse models of depression, H3K9bhb is reduced, and KD or BHB administration exerts antidepressant effects by increasing H3K9bhb levels and BDNF expression, linking BHB and BDNF via H3K9bhb." (PMID 38203294, 2023). "However, a meta-analysis reported similar (lower) plasma BDNF in patients with MDD and bipolar depression, compared to euthymic patients." (PMID 37759825, 2023). "Previous research reported that the levers of BDNF and p-CREB were decreased in the medial prefrontal cortex of comorbidity model with characteristics of both depression and chronic pain induced by DSS and CUS or single DSS." (PMID 36936941, 2023). "Esketamine decreases the number of activated microglia cells and improves depression-like behaviors in a postoperative depression (POD) model, via the BDNF/TrkB/NF-κB signaling pathway." (PMID 36776829, 2023). "The intricate interplay of the NF-κB, BDNF, MAPK, cAMP, and PI3K/Akt signaling pathways forms a complex regulatory network during the development of depression." (PMID 37932977, 2023).
depression (continued). "Puerarin, a phytoestrogen extracted from Pueraria plants, holds potential for treating depression-like behavior induced by ovariectomy, with mechanisms involving the inhibition of HPA axis hyperactivity, regulation of BDNF expression, and promotion of AHN." (PMID 38152691, 2023). "Using an adapted version of the MBCT protocol, Augmented Mindfulness-Based Cognitive Therapy, an increase in BDNF and NGF was found in the experimental group in a controlled study involving 160 patients with unipolar depression." (PMID 38250270, 2023). "Recent systematic reviews consistently found support for the link between the DNA hypermethylation of brain-derived neurotrophic factor (BDNF) and depression." (PMID 37317308, 2023). "It has also been recognized that there is a relationship between the brain levels of neurotropic factors including brain‐derived neurotrophic factor (BDNF) and depression." (PMID 37537722, 2023). "Hence, according to the neurotrophic hypothesis of depression, the presumably slower production of BDNF protein in RLA rats may, in turn, lead to a deficit in the synaptic release of BDNF and reduced target-derived support to promote the synaptic contacts with the mossy fibers." (PMID 37298449, 2023). "The outcomes were depression, anxiety, symptom checklist-90-R (SCL-90-R), quality of life, self-esteem, stress, loneliness, and BDNF concentrations." (PMID 36751189, 2023). "In depression, there exists bidirectional regulation between the hyperactivity of the HPA axis and BDNF expression." (PMID 37932977, 2023). "Evidence from animal studies using GF, antibiotic-treated, depression models, and FMT mice has also demonstrated lower levels of BDNF in the hippocampus and cortex than in healthy controls." (PMID 37139495, 2023). "Several studies have reported on the modulation of the BDNF signaling pathway by bioactive components of TCM that foster AHN and alleviate depression." (PMID 38152691, 2023). "After administration of vehicle, DEX, or OT + DEX daily for 8 weeks, the animals were assessed for anxiety-and depression-like behavior tests (OFT, elevated plus maze test (EPMT), and FST) and for expression of pCREB and BDNF in the hippocampus." (PMID 37781095, 2023). "Particularly, sodium butyrate was reported to significantly improve depression-like behaviors in CUMS-induced mice at least in part via increasing brain 5-HT level, BDNF expression, and improving Blood–brain barrier (BBB) impairments." (PMID 37759312, 2023). "Serum levels of BDNF were significantly lower among patients with DM, T2DM, DM with depression, and DM with retinopathy than the controls." (PMID 36787304, 2023). "In the present study, we investigated changes in BDNF levels and glutamate release over the duration of CMS and assessed their correlation with depression-like behaviors." (PMID 37989582, 2023). "A negative correlation was observed between the BDNF protein concentration and the severity of depression symptoms assessed with BDI; the expression of BDNF mRNA was positively correlated to the questionnaire score in IBD subjects." (PMID 36984890, 2023). "In this regard, with an adapted version of MBCT for unipolar depression, an increase in plasma BDNF has been found, which is consistent with the fact that MBCT has demonstrated clear evidence for clinical symptoms in unipolar depression." (PMID 38250270, 2023). "An animal experiment showed that the ERK pathway in the hippocampus was inhibited upon depression, and ERK regulated BDNF and cAMP response element-binding protein (CREB), two players that are key in regulating depression." (PMID 37239191, 2023). "Neurotrophins best studied in the context of OAB and depression, i.e., NGF and BDNF, are responsible for sensory afferent nerve plasticity." (PMID 36835228, 2023). "The serum levels of BDNF, NT-3, and 5-HT in patients and clinical data of MHD patients with different degrees of anxiety and depression were compared." (PMID 37750080, 2023).